GZMB (granzyme B)
Diseases named in the same sentence as GZMB in open-access papers (continued):
Sharing a sentence is not in itself a finding about the gene and the disease.
lymphoma (continued). "al. also noted the increased expression of STAT3, GZMB and TNFRSF8 (CD30) as important markers of the HIV+ lymphomas." (PMID 40627772, 2025). "Consistent with our results with NALM6, we show that both lymphoma cell lines (Daudi and Raji) are sensitive to combined GZMA and GZMB inhibition, most likely attributed to their minimal Fas surface expression." (PMID 38307835, 2024). "PTCL-NOS is CD3+ in small and large cells, and NK/T-cell lymphoma shows angiocentricity with necrosis with lymphoma cells positive for CD3, CD8, CD56, and cytotoxic markers (TIA-1, granzyme-B, perforin)." (PMID 37958219, 2023). "PTCL-NOS with large cells is CD3+, and NK/T-cell lymphoma shows angiocentricity with necrosis with lymphoma cells positive for CD3, CD8, CD56, and cytotoxic markers (TIA-1, granzyme-B, perforin)." (PMID 37958219, 2023). "This was demonstrated by an augmented release of IFN-γ and granzyme B, increased expression of the degranulation marker CD107a, fewer PD-1 + TIM-3+ CAR T cells in vitro and enhanced lymphoma cell killing both in in vitro and in vivo xenograft models." (PMID 33666760, 2021). "In two cases, the lymphoma cells expressed CD3, CD7, and Granzyme-B." (PMID 37345080, 2023). "SPTCL is distinct from primary cutaneous γ/δ T-lymphomas, which are typically CD4-, CD8-, CD56+, granzyme B+, perforin+, TIA1+, may involve the epidermis and/or dermis, may present with panniculitic pattern and invariably have a very poor prognosis." (PMID 31311562, 2019). "Therefore, we next determined whether levels of perforin, granzyme B, or cytokines TNF-α or IFN-γ would be affected by exposure of NK cells to lymphoma exosomes or survivin protein." (PMID 33513976, 2021). "Similarly, combinatory treatments with CpG-Stat3 siRNA and PD-1 antibody in A20 lymphoma tumor-bearing mice led to significantly higher percentages of activated CD8+ T cells positive for IFNγ, CD107α, which measures T cell cytotoxicity, and GZMB at the tumor sites." (PMID 39618825, 2024). "The lymphoma cells were small to medium-sized and resulted as positive, in all patients, for CD3, CD2, CD7, and TIA1 and negative for ALK, CD56, CD57, granzyme-B, and Perforin." (PMID 37345080, 2023). "BM flow cytometry gating on the lymphoma cells confirmed the positive expression of CD2, CD3, CD7, CD8, CD56, T‐cell receptor (TCR) alpha‐beta chains, perforin, granzyme B, and negative for CD34, CD4, CD5, and TCR gamma‐delta chains, consistent with natural killer (NK)/T lymphoma involvement." (PMID 37206287, 2023).
malaria (28 papers, 2012 to 2026). Malaria is a serious and sometimes fatal disease caused by a parasite that commonly infects a certain type of mosquito which feeds on humans. "Other genes previously associated with malaria pathogenesis, GZMB, FOS and HSPA6, were also higher among severe cases." (PMID 26961973, 2016). "Interestingly, a substantial fraction of these CD73+ B cells also expressed IgM and granzyme B, a biomolecule that has been increasingly associated with protective responses against malaria." (PMID 32886698, 2020). "Additionally, decreasing levels of granzyme B has been associated with a Th2 response, whereas, increasing levels in malaria have been observed in children with severe and uncomplicated infections." (PMID 33281757, 2020). "PD1+ NK cells were the most highly activated NK cells during malaria, and had high granzyme-B and perforin expression, consistent with retained cytolytic capacity." (PMID 37968278, 2023). "Granzyme B levels in the plasma were significantly higher in children with febrile malaria than in afebrile children." (PMID 31921176, 2019). "Conversely, children with uncomplicated malaria showed a higher proportion of CD4+ T cells expressing CD39 and Granzyme B, compared to children with complicated malaria." (PMID 29555909, 2018). "We found that CD8+CD28+GzmB+ T cells were enriched in malaria patients compared to healthy controls and patients suffering from AIH, PBC, PSC or chronic HBV infection." (PMID 30483269, 2018). "During blood-stage malaria, degranulation of Granzyme B, perforin, and exacerbated levels of proinflammatory cytokines such as TNF-α and INF-γ are involved with the damage to the blood–brain barrier." (PMID 28261571, 2017). "The FOS and GZMB genes were also found to be expressed at elevated levels in severe malaria cases in this study (by 2.09- and 2.31-fold, respectively)." (PMID 26961973, 2016). "Notably, CD16+ Vδ2 T cells from malaria-exposed individuals phenotypically resemble mature NK cells, including expression of the cytolytic effector molecules perforin, granzyme B and granulysin, as well as CX3CR1 and KIRs, and down-regulation of IL18R." (PMID 33085728, 2020). "CD8+ T cells were the main T cell subset expressing granzyme B. The proportion of granzyme B+ CD8+ T cells was significantly higher in children with complicated malaria than in uncomplicated malaria, whereas the activation marker CD38 on CD8+ T cells showed similar expression levels." (PMID 31921176, 2019). "As part of a cross-sectional malaria study in Ghana, granzyme B levels and CD8+ T cells phenotypes were compared in the peripheral blood of children with complicated malaria, uncomplicated malaria, afebrile but asymptomatically infected children and non-infected children." (PMID 31921176, 2019). "CD8+ T-cell-mediated responses seem to be of major importance in the anti-parasitic T-cell responses and our findings of enhanced granzyme B levels could reflect an anti-malaria effect in these patients." (PMID 30563486, 2018). "T-cell exhaustion is an important feature of severe malaria and granzyme B and in particular TIM-3 could also be markers of this process." (PMID 30563486, 2018). "In addition to anti-viral ITs, the targeted delivery of granzyme B to Plasmodium falciparum provided the first evidence of granzyme B’s anti-parasitic effects on malaria." (PMID 30622524, 2018). "It was previously shown that GzmB levels are elevated in individuals with severe malaria." (PMID 22438997, 2012). "Notably, complement genes (C1QA, C1QB, C1QC), apoptotic genes (PDL1, PDL2, APOL1, APOL2, FAS), inflammatory caspases (CASP1, CASP5), TLR pathway genes (TLR1, TLR4, TLR5, TLR8), cytokines (IL6, IL10), and granzyme (GZMB) were among the genes upregulated during symptomatic malaria." (PMID 39161730, 2024). "Granzyme-B, ICOS and HLA-DR expression was higher on Vδ2+ compared to Vδ1+ γδ T cells during malaria." (PMID 37968278, 2023).
malaria (continued). "In murine malaria it was clearly shown that CD8+ T cells sequester in the brain and mediate endothelial leakage in a granzyme B (GrzB) and perforin-dependent cytolytic reaction." (PMID 31921176, 2019). "Subsequently, we analyzed the expression of the cytotoxic molecule GzmB and Perforin the proliferation marker Ki67 and the co-inhibitory receptor PD-1, both in CD8+CD160+ and CD8+CD160− T cells from healthy controls or malaria patients." (PMID 30483269, 2018). "Differentially expressed probes form these canonical pathways that were previously shown to play a role in severe malaria pathogenesis were TLR2, TLR4, TLR8, HSPA6, CR1, C1qA, C1qB, C1qC, FOS, and GZMB." (PMID 26961973, 2016). "The higher expression of the TLR genes, GZMB, FOS, HSPA6, and CR1, in uncomplicated malaria cases during the late convalescence time point can be interpreted two ways." (PMID 26961973, 2016). "In the same line, it has been reported that protection against pox-virus, Leishmania major malaria, and tuberculosis may also be T-cell-mediated, with various functions such as IFN-γ, IL-2, TNF-α, and granzyme B being potentially involved." (PMID 41012118, 2025). "Similarly, in malaria these genes were either only modestly upregulated (GZMA and GZMB) or were downregulated (GZMH, GNLY and PRF1), compared to HS (P < .05)." (PMID 33793565, 2021). "Likewise, the negative correlation observed between Granzyme B and IL-17A may have resulted from the low levels of granzyme B observed in malaria-infected children." (PMID 33281757, 2020).
Sepsis (27 papers, 2012 to 2025). Sepsis is defined as life-threatening organ dysfunction caused by a dysregulated host response to infection. "In conclusion, plasma granzyme B demonstrated fair short-term mortality prediction among patients with sepsis in the ICU, suggesting its potential utility for risk stratification and managing patients with sepsis." (PMID 40094854, 2025). "The mechanism through which granzyme B is associated with sepsis is as follows: Granzyme B influences cytokine activation by cleaving IL-1α precursors, enhancing its pro-inflammatory effects." (PMID 40094854, 2025). "Recently, an association has been reported between high serum granzyme B concentration and high mortality rate in patients with sepsis after controlling for diabetes mellitus, sepsis-related organ failure assessment, lactic acid level, and age." (PMID 40094854, 2025). "Deficiency of gzmA and/or gzmB was associated with increased bacterial loads, especially in the case of gzmB at the primary site of infection at late stage sepsis." (PMID 28694562, 2017). "The expression level of GZMB in sepsis may be associated with the underlying pathogen." (PMID 36618365, 2022). "The ability of these factors, including plasma granzyme B, to predict 28-day mortality in patients with sepsis was statistically significant, except for IL-6." (PMID 40094854, 2025). "Future studies incorporating a larger and more diverse group of patients with varying severity degrees of sepsis are warranted to better understand the role of granzyme B as a prognostic marker." (PMID 40094854, 2025). "Future research is needed to explore granzyme B’s role in immune exhaustion during sepsis and investigate strategies to inhibit or modulate granzyme B to restore immune function and improve outcomes." (PMID 40094854, 2025). "This study aimed to elucidate the clinical implications of granzyme B in critically ill patients with sepsis, focusing on plasma granzyme B levels as a potential prognostic marker." (PMID 40094854, 2025). "This suggested that baseline granzyme B holds greater clinical significance in sepsis prognosis than short-term changes following treatment." (PMID 40094854, 2025). "This study evaluated the significance of granzyme B as a short-term prognostic predictor in medical ICU patients with confirmed sepsis, comparing it with established biomarkers." (PMID 40094854, 2025). "This study revealed that granzyme B level exhibited a predictive ability for 28-day mortality comparable to that of other well-established prognostic factors in patients with sepsis, such as lactate and SOFA score." (PMID 40094854, 2025). "Understanding the role of granzyme B in inflammatory responses in patients with sepsis has significant implications for its potential as a prognostic marker and novel therapeutic approach." (PMID 40094854, 2025). "Granzyme B has potential as a biomarker for immune dysregulation in sepsis, reflecting both inflammation and immune cell apoptosis." (PMID 40094854, 2025). "Despite granzyme B’s potential significance, research on the prognostic value of granzymes in patients with sepsis is limited." (PMID 40094854, 2025). "The present study revealed that plasma granzyme B levels were elevated in sepsis patients with poor 28-day survival and independently associated with short-term mortality, regardless of age, CCI, and SOFA score." (PMID 40094854, 2025). "By revealing a causal link between sepsis and CFHR5, FCER2, GZMB, HLA-DQA2, MBL2, or MPO, our study offers an essential resource for additional investigations on the subject." (PMID 39252215, 2024). "Some studies reported that GZMB is involved in the coagulation cascade, regulating the function of platelets and endothelial barrier permeability in sepsis." (PMID 39654893, 2024). "Our findings showed that the expression of RETN, S100A12, IL18R1, and KL was higher in the sepsis group, while the expression of GZMB, HLA-DPA1, CD3E, IL2RB, CD3G, and CCR3 was higher in the control group." (PMID 38124071, 2023).
Sepsis (continued). "As shown in these figures, the expression levels of RETN, S100A12, IL18R1, and KL were higher in the sepsis group, while that of GZMB, HLA-DPA1, CD3E, IL2RB, CD3G, and CCR3 were higher in the normal group (p < 0.05)." (PMID 38124071, 2023). "Recent studies reported that GZMB is involved in the coagulation cascade, regulating the function of platelets and endothelial barrier permeability in sepsis." (PMID 36618365, 2022). "According to the ROC curves, four out of six genes (GZMB, CHMP7, NLRP1, and AIM2) had good diagnostic value in the diagnosis of sepsis, with AUC > 0.9 in both the GSE65682 and GSE95233 datasets." (PMID 36618365, 2022). "Four out of six genes (GZMB, CHMP7, NLRP1, and AIM2) also have potential diagnostic value in sepsis diagnosis." (PMID 36618365, 2022). "To gain insight into the role of gzmA and gzmB in peritonitis and sepsis, we first sought to ascertain the expression of these gzms before and during E. coli peritonitis." (PMID 28694562, 2017). "Both gzmA and gzmB plasma levels have been found elevated in patients with diverse parasitic, viral, and bacterial infections and with severe sepsis, as well as in healthy individuals with experimentally induced endotoxemia." (PMID 28694562, 2017). "Following CLP-induced polymicrobial sepsis (severe model), granzyme B null mice (n = 5) had lower sepsis scores than wild type mice (n = 4) at every time point." (PMID 22844498, 2012). "Collectively, these findings extend our previous work identifying platelet granzyme B-based cytotoxicity in septic humans and mice and raise interesting questions regarding the role of GPIIb/IIIa blockade in sepsis." (PMID 22844498, 2012). "We previously reported an acute sepsis-induced cytotoxic platelet phenotype expressing serine protease granzyme B. We now aim to define the site(s) of and mechanism(s) by which platelet granzyme B induces end-organ apoptosis in sepsis." (PMID 22844498, 2012). "In 28-day nonsurvivors, a trend of decreasing plasma granzyme B levels during treatment was observed, distinct from survivors, highlighting the greater clinical significance of baseline granzyme B levels in sepsis prognosis compared to short-term changes following treatment." (PMID 40094854, 2025). "During sepsis, platelets, a crucial player in sepsis pathophysiology, can express granzyme B, which may contribute to endothelial dysfunction and immune dysregulation, further exacerbating disease severity." (PMID 40094854, 2025). "GNLY, GZMB, PRF1, and RASGRP1, which are lysosome-related genes, are closely linked to the prognosis of sepsis and could potentially serve as novel research targets for sepsis, offering valuable insights for the development of lysosome-targeted therapy." (PMID 38057716, 2023). "Then, we developed a prognostic risk score with six pyroptosis-related genes, including GZMB, CHMP7, NLRP1, MYD88, ELANE, and AIM2, and found that it could predict the prognosis of sepsis patients." (PMID 36618365, 2022). "An upregulation of GZMB was found in patients with gram-negative bacterial infection, while a downregulation of GZMB was found in sepsis patients caused by burns and trauma." (PMID 36618365, 2022). "While the Granzyme B expression ratio on CD4+T cells was lower in severe sepsis patients (P=0.026)." (PMID 35898496, 2022). "This was found in one of their previous study, in which they reported acute sepsis-induced cytotoxic platelet expression of a granzyme B. Eptifibatide inhibits granzyme B-mediated apoptosis in the spleen and lung, which ends up slowing the progression of sepsis." (PMID 35774677, 2022). "This would explain why GzmB deficiency does not protect from sepsis, but would not explain the increased resistance of GzmM deficient mice to endotoxicosis and the reduced coagulation activity observed in these mice." (PMID 32655547, 2020). "GzmB is able to enhance the proinflammatory activity of IL-1α by proteolytic cleavage, although GzmB deficiency does not protect from sepsis." (PMID 32655547, 2020).
Sepsis (continued). "Recent studies have found that GzmA, GzmB, GzmK, and GzmM act as pro-inflammatory mediators and could be involved in the pathophysiology of sepsis." (PMID 32655547, 2020). "During sepsis platelets carry intracellular granzyme B, probably due to transcriptional alterations in megakaryocytes, which causes local apoptosis at sites of platelet accumulation such as the lungs, spleen, and kidneys, contributing to multiple organ dysfunction and sepsis progression." (PMID 31379873, 2019). "Thus, we sought to address the extent to which sepsis altered the steady state expression of Granzyme B (GzmB) in NK-cells." (PMID 30379932, 2018). "In the present study, we aimed to investigate the role of gzmA and gzmB in the host response to E. coli-induced peritonitis and sepsis using a murine model, analyzing the local and systemic inflammatory response and damage in wild-type (WT) mice and mice deficient in gzmA, gzmB, or both gzms." (PMID 28694562, 2017). "Similarly, Eptifibatide was found to inhibit platelet granzyme B-mediated apoptosis in sepsis models." (PMID 24086587, 2013). "In summary, during sepsis, platelet granzyme B-mediated apoptosis occurs in spleen and lung tissue." (PMID 22844498, 2012). "In addition to determining sites of platelet granzyme B-induced apoptosis in sepsis, we also determined vital mechanistic aspects of this process." (PMID 22844498, 2012). "First, while we previously demonstrated that granzyme B is increased in human pediatric sepsis patients and although CLP and cecal slurry are validated animal models, whether apoptosis progresses the same in mice as in humans is not clear." (PMID 22844498, 2012). "In contrast, GzmB deficiency did not affect LPS-induced endotoxicosis or bacterial-induced sepsis." (PMID 32655547, 2020). "NK cells have been involved in sepsis and thus unregulated NK cells responses leading to a high release of GzmB due to PAMP-induced activation of NK cell receptors could transform a physiological protective mechanism into a pathological insult affecting endothelial cell permeability." (PMID 32655547, 2020). "Thus, it could be speculated that GzmB of Treg cell could contribute to the cellular immunosuppression observed in sepsis patients." (PMID 32655547, 2020). "Finally, we assessed whether HIV co-infection also impacts on plasma levels of circulating granzyme A and granzyme B in ICU patients with sepsis." (PMID 26871709, 2016). "We recently identified a potential etiologic factor for sepsis-related end-organ apoptosis: Acute sepsis-induced alterations in the megakaryocyte-platelet transcriptional axis result in strongly cytotoxic platelets expressing the potent serine protease granzyme B in mice and humans." (PMID 22844498, 2012). "It is possible that eptifibatide inhibits the activation of intracellular signaling pathways, leading to a decrease in the release of granules, which may contain apoptosis promoting proteins such as granzyme B. This pathway’s ability to participate in sepsis and MODS warrants further investigation." (PMID 22844498, 2012). "Although NK cell numbers also showed a decreased trend from HCs to bacteremia and sepsis patients, the expressions of functional markers (NKG2A, perforin, and granzyme B) were comparable among them." (PMID 38707899, 2024). "Survival analysis screened four genes positively correlated with sepsis prognosis, namely GNLY, GZMB, PRF1 and RASGRP1." (PMID 38057716, 2023). "The analysis revealed that GNLY, GZMB, PRF1, and RASGRP1 exhibited high expression levels in the normal control group, while their expression was low in the sepsis group." (PMID 38057716, 2023). "In both datasets, the expression level of AIM2, ELANE, and MYD88 were significantly higher in sepsis patients compared to healthy individuals, while the expression level of CHMP7, GZMB, and NLRP1 were significantly lower." (PMID 36618365, 2022).